NLRP3 (NLR family pyrin domain containing 3)
Diseases named in the same sentence as NLRP3 in open-access papers (continued):
Sharing a sentence is not in itself a finding about the gene and the disease.
heart failure (continued). "To summarize, NLRP3-mediated pyroptosis has a vital function in cardiac hypertrophy, and irisin can mitigate cardiac hypertrophy and heart failure by inhibiting the pyroptosis cascade." (PMID 33723236, 2021). "The expression of SOX2‐OT and levels of NLRP3 inflammasomes gradually increased in normal rats, and in those with heart failure and with VA‐HF." (PMID 33270361, 2021). "Currently, the NLRP3 inflammasome's influence on heart failure has been largely focused on its mediated role in IL-1 and IL-18 in heart remodeling." (PMID 34795807, 2021). "Increasing the circulating β-OHB levels by SCOT knockout in skeletal muscle reduced cardiac Nlrp3 inflammasome activation upon heart failure." (PMID 35309549, 2021). "In terms of heart failure, when exposed to ischemia-reperfusion injury, mice that lack the NLRP3 gene have a smaller infarct size and better cardiac function than wild-type mice." (PMID 32358544, 2020). "We postulated that pharmacological targeting of REV-ERB after myocardial ischemia–reperfusion downregulates the NLRP3 inflammasome, leading to less reperfusion injury, reduced cardiac remodeling, and protects against heart failure (HF)." (PMID 31602405, 2019). "Studies have shown that inhibiting NLRP3 is a feasible strategy to reduce adverse cardiac remodeling and improve left ventricular function in patients with heart failure, and blocking the NLRP3 inflammatory pathway has potential benefits for patients with heart failure." (PMID 40076760, 2025). "Canakinumab, conversely, demonstrated the ability to block NLRP3 inflammasome and IL-1β activations, highlighting IL-1-targeted therapy potential in preventing the recurrence of atherosclerotic thrombotic events and heart failure happening." (PMID 38650918, 2024). "Conversely, a study of salt-sensitive Dahl rats with heart failure with preserved ejection fraction (HFpEF) demonstrated that inhibition of the NLRP3 inflammasome with dapansutrile reduces atrial fibrillation (AF) by decreasing atrial inflammation and improving calcium handling." (PMID 39594530, 2024). "Thus, inhibiting the Ca2+-dependent activation of NLRP3 inflammasomes and reducing cardiac inflammation have been shown to be beneficial in treating heart failure." (PMID 38378646, 2024). "However, in a heart failure mouse model, prolonged elevation of circulating ketone body levels alleviated NLRP3 inflammasome-mediated myocardial inflammation and improved cardiac function." (PMID 39512825, 2024). "Notably, results indicates that NLRP-3 mediated pathways are involved in combinatorial ICIs –mediated cardiotoxic events; these data are in line with literature describing NLRP-3 as key driver of myocarditis, heart failure and arrhythmias." (PMID 38322766, 2024). "Moreover, recent studies have emphasized the complex relationship between NLRP3 inflammasome activation and the progression of heart failure." (PMID 39594530, 2024). "Given that NLRP3 inflammasome is a key driver of vascular disease and heart failure, it appears that enhanced NLRP3 signaling via Cx43 hemichannels may be implicated in pulmonary artery remodeling and endothelial, as well as RV, dysfunction." (PMID 38542257, 2024). "In mice, binding of bile acids to TGR5 inhibits the NLRP3 inflammasome activation thus preventing inflammation, and also enhances the heart’s ability to adapt to hemodynamic stress in heart failure via activation of pro-survival kinases and heat shock proteins." (PMID 37626809, 2023). "Furthermore, MCC950 (a specific inhibitor of the NLRP3 inflammasome) prevents heart failure by suppressing NLRP3 inflammasome and IL-1β release." (PMID 38270118, 2023). "However, empagliflozin reduce cardiac inflammation in rats with heart failure and exert a cardioprotective effect by inhibiting the NLRP3 inflammasome." (PMID 37370025, 2023).
heart failure (continued). "Given the current inefficiency in DCM therapy, targeting P2X7R and NLRP3 inflammasome or/and the related pyroptosis might be an effective alternative therapeutic strategy for chronic cardiomyopathy and heart failure." (PMID 36361807, 2022). "NLRP3 inhibition has a definite protective effect in ATP6AP2 knockdown-induced heart failure." (PMID 35379787, 2022). "We have proved that ATP6AP2 knockdown increased NLRP3 expression in TAC-induced heart failure." (PMID 35379787, 2022). "Thus, inhibiting Nlrp3 inflammasome formation can have positive effects, such as reduction of infarct size and prevention of heart failure." (PMID 35309549, 2021). "It remains to be elucidated whether irisin can ameliorate cardiac hypertrophy and heart failure by inhibiting NLRP3-mediated pyroptosis." (PMID 33723236, 2021). "Thus, inhibition of the NLRP3 inflammasome can improve the symptoms of overload-stimulated cardiac hypertrophy and heart failure." (PMID 33723236, 2021). "Similarly, dapansutrile, as the inhibitor of the NLRP3 inflammasome was shown to be effective in improving left ventricular EF and exercise time after 14 days of treatment in patients with heart failure." (PMID 34948026, 2021). "This study provides a promise that targeting of the NLRP3-inflammasome could potentially be a viable therapeutic option for cardiomyopathies, AF, and perhaps other cardiovascular diseases including heart failure." (PMID 30150941, 2018). "Continued interrogation of the NLRP3 inflammasome in heart failure is likely to aid in identifying new targets for therapeutic intervention, which may act synergistically with pharmacologic chaperones to break the cycle of amyloidosis and inflammation." (PMID 26664897, 2015). "Finally, NLRP3 activation after MI contributes to adverse cardiac remodeling and heart failure." (PMID 40332346, 2025). "However, whether NLRP3 inflammasome is activated in obesity cardiomyopathy and whether its activation contributes to the progression of heart failure remains poorly understood." (PMID 39604027, 2024). "Elevated levels of β-hydroxybutyrate (β-HB) bind to the NLRP3 inflammasome, inhibiting its activity and thereby reducing the release of the inflammatory factors IL-1β and IL-18, slowing myocardial fibrosis and promoting the recovery of the ejection fraction during heart failure progression." (PMID 39512825, 2024). "Previous studies have revealed that inhibiting NLRP3 inflammasome activation in macrophages and thereby attenuating myocardial IL‐1β and IL‐18 levels effectively ameliorates myocardial ischemic injury and pressure overload‐induced heart failure and cardiac remodeling." (PMID 39604027, 2024). "NLRP3 inflammasome sets off the maturation of proinflammatory cytokines (IL-1β and IL-18) to initiate the inflammatory response and plays a key role in modulating chronic inflammation, altering the physiological adaptation of cardiomyocyte and leading to heart failure progression." (PMID 36661914, 2023). "Notably, activation of the NLRP3 inflammasome produces inflammatory factors that recruits macrophages and T cells to trigger cardiomyocyte pyroptosis and cardiac inflammation, leading to fibrosis, adverse cardiac remodeling, and even heart failure." (PMID 37370025, 2023). "Furthermore, in murine models of heart failure with TET2 deficiency in hematopoietic cells, cardiac function worsened due to the elevation of IL-1β/NLRP3 inflammasome, and the models responded better to IL-1β/NLRP3 inflammasome inhibition." (PMID 37928907, 2023). "In addition, SGLT2 inhibitors have been reported to benefit heart failure patients through IL-1β and/or NLRP3 inflammasome mechanisms, and may be used for immune modulation." (PMID 35997820, 2022).
heart failure (continued). "Therefore, oral NLRP3 inhibitors clinically used for therapy of severe gout, arthritis, and prevention of heart failure (i.e., dapansutrile) are currently proposed in the USA as a strategy to prevent acute respiratory distress syndrome and cardiovascular diseases in COVID-19." (PMID 33182653, 2020). "This includes the Nlrp3 inflammasome, leading to reduced adverse innate and adaptive post-reperfusion inflammatory responses, thereby protecting against infarct expansion and left ventricular remodeling, and thus benefiting heart structure and function and protecting against heart failure." (PMID 31602405, 2019). "In the heart failure group, NLRP3, TXNIP, Caspase-1, and IL-1β protein expressions were up-regulated, and aerobic exercise and SKQ1 down-regulated NLRP3, TXNIP, Caspase-1, and IL-1β protein expressions." (PMID 40076760, 2025). "At the same time, TXNIP-mediated NLRP3 activation was decreased, thereby alleviating TAC-induced myocardial inflammation and apoptosis in mice with heart failure." (PMID 40076760, 2025). "Additionally, ER stress has been shown to activate the NLRP3 inflammasome, leading to pyroptotic cell death in atherosclerosis, and the inhibition of ER stress has also been found to improve cardiac function in isoproterenol-induced heart failure rats by suppressing cardiomyocyte pyroptosis." (PMID 38378646, 2024). "The role of NLRP3 inflammasome (NLR family, pyrin domain-containing 3) in heart failure is well documented." (PMID 36661914, 2023). "TAC (administration for four weeks) promoted the development of heart failure, cardiac hypertrophy, and an increase in P2X7 receptor, NLRP3, and IL-1β expression in myocardial tissue." (PMID 36320147, 2022). "Therefore, we assume that the suppressive effect of MSC on NLRP3 inflammasome activation and IL-1β secretion by macrophages could be beneficial in viral myocarditis preventing disease progression to cardiac dilatation and heart failure." (PMID 29434214, 2018). "Previous studies have demonstrated that empagliflozin attenuates cardiac dysfunction by reducing NLRP3 inflammasome activation in heart failure models, and that SGLT2 inhibitors counteract NLRP3 activation via the immunomodulatory metabolite itaconate in ischemia-reperfusion injury (IRI) models." (PMID 41030847, 2025). "A previous study showed that NLRP3 deletion did not affect blood pressure in mice with pressure load‐induced heart failure." (PMID 39604027, 2024). "NLRP3 inflammasomes activation in cardiac nonimmune cells during the pathogenesis of heart failure has received increasing attention." (PMID 39604027, 2024). "Empagliflozin attenuates heart failure in experimental models of heart failure without DM by lowering intracellular Ca2+ and suppressing NLRP3." (PMID 37762961, 2023). "Overwhelming evidence links the NLRP3 inflammasome and the IL-1 cytokines with the pathogenesis of cardiovascular diseases, nonischemic injury to the myocardium, and worsening heart failure." (PMID 35052846, 2022). "How the NLRP3 inflammasome is involved in other cardiovascular diseases, such as hypertension, arrhythmia, and heart failure, remains not very clear." (PMID 32377298, 2020). "While the mechanisms involved in priming/activation of the inflammasome in the arrhythmogenic model are not clear, the cardiac failure induced by pressure overload was dependent on NLRP3 inflammasome activation by the protein kinase, CaMKIIδ." (PMID 33101273, 2020). "Hence, given the crucial function of the NLRP3 inflammasome in DCM, it may be a viable therapeutic approach to mitigate the likelihood of heart failure in diabetic patients by targeting the NLRP-3 inflammasome pathway." (PMID 39501954, 2025). "In addition, arresting NLRP3 inflammasome by administration of MCC950 blocked Isoproterenol-induced cardiac dysfunction by suppressing cardiomyocyte senescence and ameliorated heart failure (HF) in obese mice by improving the cardiometabolic dysfunction." (PMID 38421496, 2024).
heart failure (continued). "Studies on the role of the NLRP3 inflammasome in DCM patients are scarce, let alone clinical trials of NLRP3 inflammasome inhibitors, indeed, with the exception of OLT117, which is currently being investigated in a phase I clinical trial for the treatment of heart failure." (PMID 36111168, 2022). "The NLRP3 inflammasome activator, S100A9 has been identified as a promising biomarker and therapeutic target for different cancers as well as for MI and myocarditis, accentuating the relevance of evaluating the potential of anti-S100A9 compounds in clinical studies of cancer and heart failure." (PMID 36466820, 2022). "Although a large number of studies have confirmed that NLRP3 inhibitors can improve cardiac remodeling in mice with a normal diet, it is still unclear whether NLRP3 inhibitors can improve heart failure (HF) induced by pressure overload in obese mice." (PMID 35647084, 2022).
multiple sclerosis (107 papers, 2012 to 2026). A progressive autoimmune disorder affecting the central nervous system resulting in demyelination. "According to a recent study, NLRP3 inflammasome-driven neuroinflammation contributes significantly to the pathogenic development of multiple sclerosis." (PMID 40075143, 2025). "On the other hand, chronic or dysregulated activation of NLRP3 inflammasome has been shown to play a role in the progression of inflammatory diseases like gout, multiple sclerosis, and cryopyrin-associated autoinflammatory syndrome (CAPS)." (PMID 36144933, 2022). "These maladies include multiple sclerosis, systemic-onset juvenile idiopathic arthritis arising out of gain-of-function NLRP3 mutations, rheumatic maladies, and familial-type Mediterranean fever." (PMID 34443594, 2021). "NLRP3 is also implicated in other neurological conditions such as multiple sclerosis and traumatic brain injury." (PMID 31892810, 2019). "Microglia A20 deficiency also exacerbates multiple sclerosis (MS)-like disease, due to hyperactivation of the Nlrp3 inflammasome leading to enhanced interleukin-1β secretion and CNS inflammation." (PMID 29789522, 2018). "These diseases include multiple sclerosis, systemic-onset juvenile idiopathic arthritis caused by gain-of-function NLRP3 mutations, rheumatic diseases and familial-type Mediterranean fever." (PMID 26594174, 2015). "Microglia A20 deficiency exacerbated multiple sclerosis (MS)-like disease, due to hyperactivation of the NLRP3 inflammasome leading to increased interleukin-1β secretion in mice, suggesting that A20 critically controls microglia activation and inhibits inflammasome-dependent neuroinflammation." (PMID 36918862, 2023). "Dimethyl fumarate modulates mtROS, an upstream pathway associated with NLRP3 activation, and it has been clinically approved for psoriasis and multiple sclerosis, in which it reduces NLRP3-mediated neuroinflammation." (PMID 40307577, 2025). "In the pathogenesis of multiple sclerosis, the NLRP3 inflammasome plays a key role in inducing T-cell migration to the central nervous system." (PMID 40075143, 2025). "Our search terms were “NLRP3 inflammasome, multiple sclerosis, experimental autoimmune encephalomyelitis, natural compound, autophagy, small molecular compound, inflammation, mechanism, therapy”." (PMID 40242770, 2025). "Potential pharmacological application of NLRP3 inflammasome inhibition in multiple sclerosis treatment." (PMID 40242770, 2025). "In the context of multiple sclerosis (MS), the role of the NLRP3 inflammasome has been extensively studied." (PMID 40242770, 2025). "Multiple sclerosis also features defective efferocytosis of degenerated myelin and NLRP3 inflammasome activation, sustaining CNS inflammation, contributing to progressive demyelination and neurodegeneration." (PMID 41373540, 2025). "Regarding multiple sclerosis, an inflammatory demyelinating disease of the CNS, several studies suggest a general involvement of the NLRP3 inflammasome." (PMID 39683782, 2024). "This review delves into the intricate relationship between NLR inflammasomes, particularly the NLRP3 inflammasome, and the immune‐mediated neurodegenerative disease, multiple sclerosis (MS)." (PMID 39690733, 2024). "Over-activation of microglia and the NLRP3 inflammasome have been explained in the pathogenesis of multiple sclerosis." (PMID 38107502, 2023). "The inhibition of NLRP3 along with shifting microglia polarization toward the protective M2 phenotype by ketogenic diet regulates the activation of the P2X7R and TLR4/MyD88/NF-κB/NLRP3 pathways in multiple sclerosis." (PMID 37915409, 2023). "Microglia are known to display increased NLRP3 expression in inflammatory-degenerative brain diseases such as Alzheimer’s and multiple sclerosis." (PMID 36945016, 2023). "Evidence of caspase‐1 activation and gasdermin D‐mediated pyroptosis has also been observed in the CNS of multiple sclerosis patients and in animal models, further implicating NLRP3 involvement." (PMID 35137954, 2022).